HGF (hepatocyte growth factor)
Diseases named in the same sentence as HGF in open-access papers (continued):
Sharing a sentence is not in itself a finding about the gene and the disease.
colorectal cancer (continued). "Hepatocyte growth factor (HGF) is known as a pro-cancer promotor in cancer development, invasion, metastasis and drug resistance of colorectal cancer through modulating mesenchymal epithelial transition (cMET)." (PMID 35953652, 2023). "In particular, colorectal cancer patients exhibited the most significant increase in plasma HGF despite having comparable pre-surgery levels." (PMID 38067195, 2023). "Colorectal-cancer-CAFs-derived HGF induced up-regulation of CD44 which mediated adhesion of CRC cells to endothelial cells, and subsequently resulted in enhancement of metastasis of CRC." (PMID 35936516, 2022). "FAP and HGF have an important role in increasing vascularization in patients with colorectal cancer, and their expression levels are significant for predicting liver and LN metastases." (PMID 35330327, 2022). "It bears mentioning that a prior report implicated the involvement of an autocrine pathway in CCL20-CCR6 signaling in colorectal cancer cells reliant on a secreted factor other than the pathways involving HGF and MSP shown in this study." (PMID 34853656, 2021). "For example, in colorectal cancer cells (CRCs), stimulation of hepatocyte growth factor (HGF) upregulates the β-catenin expression through the PI3-K pathway." (PMID 33968932, 2021). "Our finding that signaling through the HGF/c-Met pathway induces migration of colorectal cancer cells is substantiated by several studies including those using the HT-29 and HCT116 cell lines." (PMID 34853656, 2021). "Hepatocyte growth factor (HGF) expression plays a role in the invasiveness of ovarian tumors in patients with hepatic metastases of colorectal cancer relapsing after neoadjuvant chemotherapy." (PMID 33923319, 2021). "HGF was found to induce migration of both the colorectal cancer cell lines using the wound healing assay." (PMID 34853656, 2021). "There are mixed reports on the role of HGF in inducing proliferation in colorectal cancer cells including the HT-29 and HCT116 cell lines." (PMID 34853656, 2021). "It has been suggested that ERK signalling activated by hepatocyte growth factor leads to increased COX2 expression in human colorectal cancer and non-small cell lung cancer." (PMID 32385388, 2020). "Regarding colorectal cancer, HGF induces EMT and an increase in p-ERK and AKT in the CT26 murine colorectal cancer cell line, that in turn regulates the expression of Slug." (PMID 31200510, 2019). "HGF has been described as the main mediator of stroma-induced resistance to BRAF inhibitors in BRAF mutated melanoma, colorectal cancer (CRC) and glioblastoma, by activating MAPK and PI3K/Akt signaling in tumor cells via MET receptor." (PMID 30927908, 2019). "In brief, our results showed that CC-CAFs promoted metastasis of colorectal cancer by up-regulation of CD44 through HGF/MET/AKT signal." (PMID 31367190, 2019). "Overexpression of c-met protein combined with an expression of HGF is seen in a majority of colorectal cancer cases (Liu, Li & Zhu, 2012)." (PMID 31275738, 2019). "As other pathway, Liska and colleague have reported that hepatocyte growth factor (HGF)-activating c-MET rescued EGFR inhibition in colorectal cancer cells." (PMID 28642617, 2017). "c-MET and its ligand HGF are frequently overexpressed in colorectal cancer (CRC) and increased c-MET levels are found in CRC liver metastases." (PMID 27793046, 2016). "In our in vivo models, the combination of CPT-11 with anti-HGF antibody showed a potent anti-cancer effect on human colorectal cancer, as evidenced by the strong inhibition of tumor growth and interference with c-MET signal transduction." (PMID 26090722, 2015). "In summary, HGF appears to play a substantial role in the complex mechanisms involved in the induction of chemoresistance of colorectal cancer by fibroblasts." (PMID 26090722, 2015).
colorectal cancer (continued). "By using colonic fibroblast cell line CCD-18co and chemotherapy drug CPT-11, we demonstrate that fibroblasts play a functional role in chemoresistance of colorectal cancer cells presumably through fibroblast-derived HGF in tumors via c-MET signaling." (PMID 26090722, 2015). "HGF deprivation using neutralizing antibody enhanced chemosensitivity in colorectal cancer cells (CRC)." (PMID 26090722, 2015). "In colorectal cancer, myofribroblasts in the tumor environment were found to secrete hepatocyte growth factor (HGF), which can support the stem cell population, at least in part, by activating Wnt signaling." (PMID 27158195, 2015). "The activation of HGF/c-Met signaling pathway not only can promote the spread of colorectal cancer cells, but also can promote colorectal cancer liver metastasis." (PMID 24936152, 2014). "Stromal myofibroblasts in human colorectal carcinomas are reported to produce high levels of hepatocyte growth factor (HGF), which acts via the Met receptor on nearby carcinoma cells in a paracrine fashion." (PMID 24216702, 2013). "In our studies we didn't notice any changes of HGF level in blood of liver benign tumor patients after PH however, the increase of serum HGF concentration was observed in colorectal carcinoma metastatic patients 30 min after liver resection." (PMID 14960204, 2004). "To evaluate the clinical significance of serum levels of hepatocyte growth factor (HGF) in colorectal cancer patients, we measured the venous and portal concentrations of HGF in 60 patients." (PMID 9716026, 1998). "Additionally, a case study revealed all three cases of AFP-producing colorectal cancer in which activation of the HGF/c-Met/the transcription factor c-Myc signaling pathway was observed." (PMID 38817451, 2024). "Notably, colorectal cancer patients exhibited the most significant upregulation in plasma HGF—approximately a 6-fold increase within 24 h after surgery." (PMID 38067195, 2023). "Treating the colorectal cancer cells with an ERK1/2 inhibitor during CCL20 stimulation blocked CCL20-induced migration in both colorectal cancer cell lines to the extent seen with inhibition of HGF using the anti-HGF antibody." (PMID 34853656, 2021). "We also observed that HGF induces colorectal cancer cell migration and CCL20 production." (PMID 34853656, 2021). "The HGF/c‐Met signaling pathway participates in the liver metastasis of colorectal cancer in mice." (PMID 34555268, 2021). "Similarly, the production of CCL20 induced by stimulating the colorectal cancer cells with CCL20 was abrogated by the anti-HGF antibody (4.4 fold for CCL20 versus 2.1 fold for CCL20 with anti-HGF antibody in HT-29 and 3.1 fold versus 1.4 in HCT116)." (PMID 34853656, 2021). "We first checked if HGF could induce colorectal cancer cell migration, CCL20 secretion, proliferation." (PMID 34853656, 2021). "For example, stimulation of hepatocyte growth factor (HGF) in colorectal cancer cells (CRCs) promotes phosphorylation of β-catenin in tyrosine residue and its dissociation from Met (HGFR is encoded by proto-oncogene MET) and thus upregulates β-catenin expression via the PI3-K pathway." (PMID 31921137, 2019). "In addition, HGF has been shown to induce chemoresistance in different cancer cells and serum HGF levels have been correlated with prognosis and response to targeted therapies in colorectal cancer patients." (PMID 31072019, 2019). "HGF expression in CC-CAFs was higher that of normal fibroblasts, CC-CAFs promote metastasis of colorectal cancer through HGF/c-Met which induce up-regulation of CD44 whose correlation with metastasis can be observed in clinical specimen and orthotopic liver metastatic model." (PMID 31367190, 2019). "It has been hypothesized that CAFs contribute to adhesion to endothelial cells of colorectal cancer (CRC) via HGF/c-Met pathway." (PMID 31367190, 2019).
colorectal cancer (continued). "An earlier report documented that a novel ISG, BATF2, as potent negative regulator of hepatocyte growth factor (HGF)/Met signaling in colorectal cancer and may serve as a prognostic tumor marker." (PMID 29848298, 2018). "Along with their ability to hamper HGF/MET signaling in a number of biochemical and biological assays, these antibodies displayed anti-tumor and/or anti-metastatic activity in preclinical models of HGF-dependent glioblastoma, triple-negative breast cancer, and colorectal cancer." (PMID 28548076, 2014). "MACC1 is a newly identified key regulator of HGF-MET signaling in colorectal carcinoma." (PMID 23573286, 2013). "Furthermore, we found that MACC1 acts a key regulator of the HGF (hepatocyte growth factor)/Met-pathway, which is crucial in colorectal cancer for tumor progression and metastasis formation." (PMID 23166620, 2012). "Our findings in women who later developed colorectal cancer also suggest that the observed association between CYP19A1 and HGF levels may be more relevant to cancer population." (PMID 22848710, 2012). "Therefore, we incubated SKOV3ip-lacZ human ovarian carcinoma and HCT-116 human colorectal carcinoma cells with TGF-β1 or HGF, respectively." (PMID 21541352, 2011). "Moreover, HGF level was higher in preoperative serum of patients with colorectal carcinoma liver metastases compared with those with benign tumors." (PMID 14960204, 2004). "Serum HGF seems to be a useful index of the disease status of patients with colorectal carcinoma." (PMID 9716026, 1998). "Here, the main tumor-promoting cytokines released by MDSCs, VEGF, HGF, IL-6, and IL-23 were detected, and the results showed that only IL-23 levels were significantly increased in the supernatant of MDSCs cultured with PA+MC-38-CM as well as in implanted colorectal cancer loaded with P. anaerobius." (PMID 37781363, 2023). "Taken together, our findings suggest that the fibroblast-derived HGF may play an important role in cancer cell survival and that the interference with its effect in tumor cells may represent a novel strategy for the treatment of colorectal cancers." (PMID 26090722, 2015). "In colorectal cancer, liver metastasis, CD4+FOXP3+ Tregs, and increased levels of α-smooth muscle actin, HGF, and c-MET indicate potential therapeutic targets for this metastatic form of colorectal cancer." (PMID 40281554, 2025). "SOX13 is induced by hepatocyte growth factor through the JAK2/STAT3 signaling pathway, promoting metastasis in colorectal cancer by upregulating SNAI2 and c-MET expression." (PMID 39726600, 2024). "In colorectal cancer liver metastasis, the emergence of CD4+FOXP3+ Tregs, coupled with elevated levels of α-smooth muscle Actin, HGF, and c-MET, suggests potential therapeutic targets for this metastatic variant of colorectal cancer." (PMID 39664377, 2024). "In colorectal cancer, stromal myofibroblasts were shown to promote MET expression by secreting hepatocyte growth factor and activating WNT self-renewal to maintain long-term tumor stem-cell proliferation." (PMID 37674118, 2023). "CAFs have been found to secrete cytokines such as HGF and OPN in colorectal cancer, which induce EMT." (PMID 37605453, 2023). "Overexpression of MACC1 has been demonstrated to upregulate the HGF-MET signaling pathway, which in turn promotes tumor proliferation, invasion, and metastasis in colorectal cancer." (PMID 38021160, 2023). "We demonstrate that CCL20 induces HGF-dependent ERK1/2 phosphorylation in neoplastic epithelial colorectal cancer cells and that CCL20-dependent colorectal cancer cell migration and CCL20 production are mediated by ERK1/2." (PMID 34853656, 2021). "This study demonstrates that CCL20 induces secretion of hepatocyte growth factor (HGF) and phosphorylation of HGF’s cognate receptor c-Met in HT29 and HCT116 colorectal cancer cell lines both in concentration- and time-dependent manners." (PMID 34853656, 2021).
colorectal cancer (continued). "We have identified HGF, SDF1 and OPN as the key cytokines released by CAFs able to reprogram colorectal cancer cells toward CSCs endowed with metastatic potential." (PMID 30927908, 2019). "In colorectal cancer, CAF release hepatocyte growth factor, which stimulates the self-renewal of CSCs through a β-catenin-dependent mechanism and promotes the reprogramming of colorectal cancer progenitors into CSCs." (PMID 29461491, 2018). "The overexpression of FOXC2 also can induce MET expression and stimulate the hepatocyte growth factor (HGF)-MET signaling pathway, hence inducing the metastasis and invasion of colorectal cancer cells." (PMID 30360388, 2018). "HGF neutralizing antibody effectively reduces the activation of HGF/c-MET signaling, which blocks its ability to promote CPT-11 resistance in colorectal cancer cells." (PMID 26090722, 2015). "TNF-α induces Met transcription via NF-κB and in human colorectal cancer tissues high levels of TNF-α correlate with increased Met and HGF expression, responsible for HGF/Met pro-invasive paracrine circuits in these tumors." (PMID 28548074, 2014). "Thus, the findings may not be applicable to the general population, although both CYP19A1 variants and HGF levels were not strongly associated with colorectal cancer risk." (PMID 22848710, 2012). "Metastasis-associated in colon cancer-1 (MACC1) has been newly identified to express highly in colorectal cancer (CRC) and promote tumor metastasis through transactivating metastasis-inducing HGF/MET signaling pathway." (PMID 22533346, 2012). "More recently, TNFα, Hepatocyte Growth Factor, PDGF and FGF19 and IL-1β have been shown to activate Wnt/β-catenin signaling, the oncogenic pathway activated in the majority of colorectal cancers." (PMID 20661477, 2010). "Expression of hepatocyte growth factor (HGF)-mRNA is markedly increased after portal vein ligation, which is known to stimulate growth of colorectal carcinoma cells in vitro." (PMID 19209170, 2009). "Our newly generated HGF/HGFL protease inhibitors could overcome both de novo and acquired cetuximab resistance in colorectal cancer (CRC)." (PMID 38212428, 2024). "We found that, under the regulation of the MACC1/HGF/c-MET axis, the proliferation and metastasis of colorectal cancer are increased by MACC1, which can be a novel biomarker for predicting ICIs response in colorectal cancer." (PMID 35874635, 2022). "The correlation between the HGF expression (hepatocyte growth factor) and FAP (fibroblast activation protein) with an increase in the number of blood vessels and metastasis in colorectal cancer (127 samples), colorectal polyps (51 cases), and unaltered tissues (28 cases) was studied." (PMID 35330327, 2022). "HGF could activate ERK1/2 and AKT via MET phosphorylation, resulting in cetuximab resistance in colorectal cancer patients." (PMID 35204406, 2022). "As, HGF did not induce colorectal cancer cell proliferation, inhibition of HGF also did not have any effect on the increased proliferation induced by CCL20." (PMID 34853656, 2021). "Moreover, CCL20-mediated ERK1/2 phosphorylation was inhibited by an anti-HGF antibody, implying that CCL20-dependent ERK signaling in colorectal cancer cells is mediated through HGF." (PMID 34853656, 2021). "Overall, these data, including our own findings, appear to suggest that HGF is not a powerful mitogenic factor for colorectal cancer cells, particularly the HT-29 and HCT116 cell lines." (PMID 34853656, 2021). "Similarly, we found that CCL20-dependent colorectal cancer cell migration and CCL20 production are mediated through HGF." (PMID 34853656, 2021). "Surprisingly, stimulation with HGF did not increase colorectal cancer cell proliferation at doses up to 1000 ng/ml." (PMID 34853656, 2021). "Similarly, in colorectal cancer cells, high resolution mass spectrophotometry identified TYK2 as a phosphorylation target of hepatocyte growth factor (HGF), which stimulates proliferation in these cells." (PMID 34439323, 2021).
colorectal cancer (continued). "Our results show that the correlation between HGF levels and OS is not restricted to patients suffering from colorectal cancer and being treated with mAbs." (PMID 28456787, 2017). "A clinical trial that included bevacizumab as an adjuvant in colorectal cancer reported increases in plasma levels of FGF-2, hepatocyte growth factor (HGF), placental growth factor (PIGF), stromal-derived factor (SDF)-1, and macrophage chemoattractant protein-3." (PMID 27608016, 2016). "Thus, crosstalk between hepatocyte growth factor (HGF)/c-MET and β-catenin signaling sustains and increases the invasive properties of colorectal cancer cells." (PMID 24202444, 2013). "We had chosen these metastasis biomarkers for combination, since they address most relevant signaling pathways in colorectal cancer progression and metastasis: MACC1 - a key regulator of the HGF/Met signaling pathway, and S100A4– a transcriptional target gene of the Wnt/β-catenin signaling pathway." (PMID 23166620, 2012). "The combination of the two metastasis-inducing genes, MACC1 - a key regulator of the HGF/Met signaling pathway, with S100A4– a transcriptional target gene of the Wnt/β-catenin signaling pathway, improves survival prediction for newly diagnosed colorectal cancer patients." (PMID 23166620, 2012). "At the invasive front of colorectal carcinoma the cytoplasmic accumulation of LAM5γ2 in neoplastic cells is the result of synergistic activation of the LAMC2 gene by β-catenin, TGFβ1, and hepatocyte-growth factor (HGF), molecules that all have been variably involved in the pathogenesis of IPF/UIP." (PMID 16813649, 2006). "Having shown that CCL20 induces secretion of HGF by colorectal cancer cells and that HGF can induce colorectal cancer cell migration and CCL20 secretion, we next investigated whether CCL20-dependent colorectal cancer cell migration and CCL20 production are mediated through HGF." (PMID 34853656, 2021). "The activation of the HGF pathway and the high expression of miR20a-5p has been further observed in an azoxymethane/dextran sodium sulfate (AOM/DSS) mouse model of colorectal carcinoma (CRC) and in CRC human biopsies positive for E. coli producing colibactin." (PMID 32708331, 2020).